CXCL9 (C-X-C motif chemokine ligand 9)
Diseases named in the same sentence as CXCL9 in open-access papers (continued):
Sharing a sentence is not in itself a finding about the gene and the disease.
respiratory infection (2 papers, 2018 to 2025). "Elevated BALF CXCL9 concentrations during respiratory infections markedly increased CLAD risk in a dose-response manner." (PMID 31414076, 2018). "We furthermore demonstrate for the first time, the prognostic importance of BALF CXCL9 concentrations during respiratory infections on the risk of subsequent CLAD development." (PMID 31414076, 2018). "We furthermore test a novel hypothesis regarding the importance of BALF CXCL9 concentration during respiratory infections on CLAD risk." (PMID 31414076, 2018). "Furthermore, respiratory infections with elevated BALF CXCL9 concentrations markedly increased CLAD risk in a dose-response manner." (PMID 31414076, 2018). "We furthermore find that BALF CXCL9 concentrations during respiratory infections increase CLAD risk in a dose-response manner: a single episode of respiratory infection with CXCL9 >25th, 50th, and 75th percentiles had HRs for CLAD of 1.8, 2.4, and 4.4, respectively." (PMID 31414076, 2018). "Thus, we hypothesized that BALF CXCL9 during respiratory infection would be predictive of CLAD risk." (PMID 31414076, 2018). "Furthermore, we test a novel hypothesis using BALF CXCL9 concentrations, to quantify the severity of Type 1 immune response during respiratory infections, as a prognostic marker of subsequent CLAD risk." (PMID 31414076, 2018). "The current study builds upon these prior studies by utilizing BALF CXCL9 concentrations at the time of respiratory infection to quantify the severity of Type 1 immune response and provide prognostic data in terms of subsequent CLAD risk." (PMID 31414076, 2018). "The HR for an episode of respiratory infection with CXCL9 concentration greater than the 25th percentile (364 pg/ml) was 1.8 (95% CI 1.1–2.8)." (PMID 31414076, 2018). "A single episode of respiratory infection with CXCL9 >25th, 50th, and 75th percentiles had HRs for CLAD of 1.8, 2.4, and 4.4, respectively." (PMID 31414076, 2018). "Median BALF CXCL9 were markedly elevated during respiratory infection compared to healthy samples: 2730 vs 349 pg/ml (p<0.001), respectively." (PMID 31414076, 2018). "These variables were a cumulative count of respiratory infections only where the CXCL9 concentration was greater than the specified quartile cutoff." (PMID 31414076, 2018). "An episode of respiratory infection with CXCL9 concentrations greater than the 25th, 50th, and 75th percentile had adjusted HRs for CLAD of 1.8 (95% CI 1.1–2.8), 2.4 (95% CI 1.4–4.0) and 4.4 (95% CI 2.4–8.0), respectively." (PMID 31414076, 2018). "Based on our prior studies, we hypothesized that BALF CXCL9 would be elevated during respiratory infections compared to healthy biopsies, reflecting severity of injury and thus, increase CLAD risk." (PMID 31414076, 2018). "We hypothesized that elevated BALF CXCL9 concentrations during respiratory infection would be predictive of subsequent CLAD development." (PMID 31414076, 2018). "We furthermore hypothesized that bronchoalveolar lavage fluid (BALF) CXCL9 concentrations are augmented during respiratory infections, and that episodes of infection with elevated BALF CXCL9 are associated with greater CLAD risk." (PMID 31414076, 2018). "We find that BALF CXCL9 is elevated during respiratory infection, but not during episodes of colonization." (PMID 31414076, 2018).
rickettsioses (2 papers, 2018 to 2020). "Published findings from the mouse model of rickettsiosis employed in this study yield evidence for increased expression of T cell targeting chemokines CXCL9 and CXCL10 in the lungs and infiltration of CD8+ T cells in the perivascular space around Rickettsia-infected microvessels." (PMID 30687302, 2018).
steatosis (2 papers, 2022 to 2023). Increased lipid within the cytoplasm of cells. "Liver tissues had more serious steatosis, hepatocyte ballooning degeneration, and lobular inflammatory infiltration, and the expression of SPP1 and CXCL9 in liver cells was significantly upregulated in NASH patients compared to healthy controls." (PMID 35514751, 2022).
Tinnitus (2 papers, 2023). Tinnitus is an auditory perception that can be described as the experience of sound, in the ear or in the head, in the absence of external acoustic stimulation. "The top five proteins associated with tinnitus with a p value less than 0.02 were FGF-21, MCP4, GDNF, CXCL9, and MCP-1." (PMID 38079022, 2023). "Future studies are needed to further delineate the role of CXCL9 in VS tumors and whether it could be used as a similar prognostic factor for tinnitus." (PMID 37048724, 2023). "This study observed higher expression of CXCL9 in the group with tinnitus; thus, it could be hypothesized that the cytokine activation occurring in these VS tumors elevated CXCL9 expression." (PMID 37048724, 2023).
tongue tumor (2 papers, 2021 to 2024). "Therefore, we further validated the expression of Th1-associated chemokine genes, including Cxcl9, Cxcl10, and Ccl5, and Th2/Treg-associated chemokine genes, including Ccl17 and Ccl22, in carcinogen-induced tongue tumors using qRT-PCR." (PMID 33921389, 2021).
AA amyloidosis (1 paper, 2025). Secondary amyloidosis is a form of amyloidosis, that complicates chronic inflammatory disorders (mainly rheumatoid arthritis) and is characterized by the aggregation and deposition of amyloid fibrils composed of serum amyloid A protein, an acute phase reactant. "Additionally, several confounding factors are known for CXCL9 and CXCL10, including bacterial urinary tract infections, BK polyomavirus infection, recurrent AA amyloidosis, and thrombotic microangiopathy." (PMID 41306150, 2025).
abortion (1 paper, 2025). the ending of pregnancy by removing a fetus or embryo before it can survive outside the uterus. "CD86+ cells in the placentas of the abortion group were significantly more abundant than in the normal group, whereas anti-CXCL9 treatment notably reversed this effect." (PMID 41280905, 2025). "Anti-CXCL9 treatment significantly attenuated the embryo resorption rate in LPS-induced abortion models, suggesting its therapeutic potential." (PMID 41280905, 2025). "More importantly, recent research has observed aberrant upregulation of CXCL9 in placenta tissues from spontaneous abortion patients compared to healthy pregnancies." (PMID 41280905, 2025). "Importantly, anti-CXCL9 treatment effectively reversed the expression of E-cadherin and Vimentin in the placentas of LPS-induced abortion mice." (PMID 41280905, 2025). "Although the LPS-induced abortion model demonstrated the effects of CXCL9 inhibition on embryo absorption, the systemic inflammatory effects of LPS may introduce confounding variables." (PMID 41280905, 2025). "To further confirm the role of CXCL9 in vivo, we performed animal experiments using normal pregnant mice and LPS-induced abortion models with or without anti-CXCL9 neutralizing antibody treatment." (PMID 41280905, 2025).
acute coronary syndrome (1 paper, 2025). Signs and symptoms related to acute ischemia of the myocardium secondary to coronary artery disease. "While reduced Cxcl9 expression similarly indicates suppressed myocardial inflammatory response, patients with acute coronary syndrome show decreased peripheral blood levels of this chemokine—likely due to monocyte recruitment to infarct zones, where CXCL9 serves as a potent chemoattractant." (PMID 40869420, 2025).
acute disseminated encephalomyelitis (1 paper, 2020). Acute disseminated encephalomyelitis (ADEM) is a demyelinating disorder of the central nervous system. "Experiment has shown that CoVs play a destructive role in acute disseminated encephalomyelitis (ADEM) correlated with increased inflammatory mediators such as IL-6, IFN-γ, TNF-α, CXCL9, and CXCL10." (PMID 33708124, 2020).
acute GVHD (1 paper, 2024). "Early detection of serum levels of CCL23 and CXCL9 in patients undergoing HSCT can effectively predict the risk of developing acute GVHD." (PMID 39840040, 2024). "The significant increase in the levels of CXCL9 and CXCL10 in patients’ plasma can serve as effective diagnostic biomarkers for acute GVHD." (PMID 39840040, 2024). "Specifically, the upregulation of CXCL9, CXCL10, and CXCL11 in the skin of patients with acute GVHD promotes the recruitment of eosinophils and T cells to the sites of injury." (PMID 39840040, 2024).
Acute hepatitis (1 paper, 2022). Acute hepatic injury resulting from inflammation typically accompanied by increased serum alanine transaminase activity. "Similar results have only been found in one acute hepatitis study, where CXCL9, CXCL10, CXCL11 and CXCL13 elevated during the acute phase but then decreased in conjunction with an HBsAg decline." (PMID 36304473, 2022).
amyloidosis (1 paper, 2025). A disorder characterized by the localized or diffuse accumulation of amyloid protein in various anatomic sites. "In addition, levels of CXCL9 and HGF were higher in patients with ATTR-CM than in patients with HF without amyloidosis." (PMID 40570404, 2025).
anemia (1 paper, 2023). A reduction in the number of red blood cells, the amount of hemoglobin, and/or the volume of packed red blood cells. "Malaria infection during pregnancy leads to severe maternal anemia and low infant birth weight, and multivariate analysis of known predictors of birth weight suggests that elevated placental CXCL9 levels are considered an important cause of fetal growth restriction." (PMID 37033160, 2023).
anthrax (1 paper, 2010). "Consistent with its potent antimicrobial activity in vitro and its sustained induction within the lungs following spore challenge in vivo, neutralization of endogenous CXCL9 resulted in significantly increased host susceptibility to inhalational anthrax." (PMID 21124994, 2010). "Combinatorial neutralization of CXCL9 together with CXCL10 or CXCL10/CXCL11 during pulmonary B. anthracis infection significantly increased host susceptibility to anthrax, with neutralization of all three CXC chemokines resulting in 50% mortality (p = 0.0003)." (PMID 21124994, 2010). "As the induction of the interferon-inducible ELR- CXC chemokines within the lungs of spore-challenged mice is associated with resistance to inhalational anthrax, we sought to determine whether murine CXCL9, CXCL10, and CXCL11 exert antimicrobial activity against B. anthracis Sterne strain." (PMID 21124994, 2010). "To gain insight into disease progression associated with the neutralization of CXCL9, CXCL10, and CXCL11, and to confirm that host death resulted as a consequence of B. anthracis infection, we investigated two salient features of anthrax: bacterial dissemination and toxemia." (PMID 21124994, 2010). "Similarly, and of particular relevance to the current study, adults exposed to B. anthracis spores (based on positive nasopharyngeal swab cultures) in the U.S. Capitol building during the 2001 anthrax attacks demonstrated elevated levels of several inflammatory mediators including CXCL9." (PMID 21124994, 2010).
apical periodontitis (1 paper, 2022). "Similarly, in an apical periodontitis mouse model, CXCL9, the CXCR3 ligand is expressed in macrophages in the periapical tissue." (PMID 35794867, 2022).
atopic asthma (1 paper, 2023). An asthma that is characterized by symptoms that are triggered by an allergic reaction caused by inhaled allergens such as dust mite allergen, pet dander, pollen and mold. "In this study, we compared changes in serum levels of IL-4 and T1 chemokines and their association with CXCL9 according to the age-related presence of atopic asthma." (PMID 37005469, 2023). "The multiple regression models, including sex, atopic asthma, and medication steps, also supported age-related CXCL9 levels induction, IL-4 levels, and the atopic asthma ratio reduction." (PMID 37005469, 2023). "Multiple regression analysis with age as the dependent variable and CXCL9, IL-4, sex, treatment steps, and atopic asthma as explanatory variables revealed that CXCL9 concentrations, IL-4, and atopic asthma were significantly related to age." (PMID 37005469, 2023).
autoimmune encephalitis (1 paper, 2022). Inflammation of the brain secondary to an immune response triggered by the body itself. "Also, there was a significant difference between infectious and autoimmune encephalitis regarding CSF levels of IL-10 and CXCL9." (PMID 36048783, 2022).
autoimmune myocarditis (1 paper, 2025). Autoimmune myocarditis is an autoimmune disease that affects the heart. "Rapamycin preserves cardiac function in autoimmune myocarditis by reprogramming Cxcl9+ macrophages via the mTORC1–C/EBPβ–OSM axis." (PMID 41412038, 2025).
autoimmune pancreatitis (1 paper, 2024). "A positive feedback loop consisting of IFN-alpha CXCL9, CXCL10, and CCL25 mediates experimental and human autoimmune pancreatitis." (PMID 39264798, 2024).
bacterial pneumonia (1 paper, 2025). Acute infection of the lung parenchyma caused by bacteria (e.g., Streptococcus pneumoniae, Haemophilus influenzae, Chlamydia pneumoniae, Mycoplasma pneumoniae, and Legionella pneumophila). "The CCL18, CXCL9, CXCL10, CXCL11, and MMP9 levels were also elevated in patients with other respiratory diseases, such as bacterial pneumonia and COPD." (PMID 40269953, 2025).
BK-virus nephropathy (1 paper, 2022). "CXCL9 has previously been shown to have diagnostic potential as urine biomarker within TCMR and BK virus nephropathy together with CXCL10." (PMID 35204399, 2022).
bladder tumors (1 paper, 2015). "We observed that bladder tumors uniformly expressed only low levels of CTL attracting chemokines: CCL5, CXCL9, and CXCL10 (respective ligands for CTL-expressed CCR5 and CXCR3)." (PMID 25806105, 2015).
brain inflammation (1 paper, 2013). "Several immune cell chemoattractants (Ccl4, Ccl7, Cxcl9) are featured in this network, suggesting recruitment of monocytes, NK cells and T-cells to the site of brain inflammation." (PMID 23853600, 2013).
cholangitis (1 paper, 2024). An acute or chronic inflammatory process affecting the biliary tract. "For example, testosterone suppressed hepatic inflammation by downregulating IL-17, CXCL9, and CXCL10 in an acute cholangitis model." (PMID 38338982, 2024).
chordoma (1 paper, 2025). Chordomas are rare malignant tumors arising from embryonic remnants of the notochord in axial skeleton. "The expression analysis identified significant downregulation of SPOCK3, NRK, MYH8, DLK1 and SLN, alongside upregulation of HLA-DQA1, GDA, CXCL11, CXCL9 and ADAMDEC1 in chordomas." (PMID 40386066, 2025).
chronic hepatitis (1 paper, 2024). An active inflammatory process affecting the liver for more than six months. "The slopes of CXCL9, CXCL10, CXCL11, and TIGIT were higher in T cells of chronic hepatitis patients than in those of patients with HBeAg+ chronic infection and HBeAg− chronic infection, indicating that the expression of these genes was increased in the corresponding cell types." (PMID 39135698, 2024).
cognitive decline (1 paper, 2023). "Increased expression of CXCL9 in the serum and CSF has been associated with cognitive decline and is increased in AD brain." (PMID 37304071, 2023).
colon adenocarcinoma (1 paper, 2018). "In addition, human colon adenocarcinomas express high levels of mRNA CXCR3 ligands and tumor endothelial cells produce CXCL9 and CXCL10 ex vivo." (PMID 29671006, 2018).
congenital toxoplasmosis (1 paper, 2020). Toxoplasma infection that is present from birth. "Moreover, the combined stepwise analyses of CD4+CD25+ T-cells and CXCL9 or the total frequency of in vitro IFN-γ-producing T. gondii-specific T-cells further improve the accuracy of the diagnosis of congenital toxoplasmosis." (PMID 33028847, 2020). "Combined analyses of CD4+CD25+ T-cells and CXCL9, and IFN-γ production by CD4+ and CD8+ T-cells have even higher accuracy as biomarkers of congenital toxoplasmosis." (PMID 33028847, 2020). "We propose the levels of CXCL9 and CXCL10, the frequencies of CD4+CD25+ T-cells and the frequency of T. gondii-specific IFN-γ producing CD4+ T-cells presented as biomarkers able to distinguish with high accuracy infants with congenital toxoplasmosis from uninfected healthy controls." (PMID 33028847, 2020).
cutaneous sarcoidosis (1 paper, 2023). "The implication of IFN-γ on Mɸ in human skin is underlined by its effects on Mɸ immunologic reprofiling: in cutaneous sarcoidosis, IFN-γ-related expression of downstream translational targets includes STAT1, CEBPB, FN1, TREM1, CXCL9, CXCL10, IL-6, and others." (PMID 36902053, 2023). "The role of IFN-γ in cutaneous sarcoidosis is reinforced by the observation that IFN-γ-inducible chemokines CXCL9 and CXCL10 are elevated in serum and tissue of patients with systemic sarcoidosis, and blood transcriptional profiles show IFN-γ-related signaling pathways in such patients." (PMID 36902053, 2023).
dacryoadenitis (1 paper, 2018). Inflammation and enlargement of the lacrimal gland. "Thus, type I IFN signaling contributed to the male-specific upregulation of disease-relevant genes (Cxcl9, Ccl19, Epsti1) and was required for dacryoadenitis development in male NOD mice." (PMID 30347820, 2018). "We found that upregulation of Cxcl9, Ccl19 and Epsti1 was altered in NOD mice deficient in type I IFN signaling and these mice also failed to develop dacryoadenitis." (PMID 30347820, 2018). "While Treg-depletion was not sufficient to drive dacryoadenitis in castrated male NOD mice, chemokines (Cxcl9, Ccl19) and other potentially disease-relevant genes (Epsti1, Ubd) were upregulated in male lacrimal glands." (PMID 30347820, 2018).
delirium (1 paper, 2025). A disorder characterized by confusion; inattentiveness; disorientation; illusions; hallucinations; agitation; and in some instances autonomic nervous system overactivity. "Univariate analysis revealed that elevated levels of CXCL10, CXCL9, and CXCL8 were linked to an increased delirium risk." (PMID 38861234, 2025). "In our research, we found higher levels of CXCL8, CXCL9, and CXCL10 to be associated with delirium in univariate analysis." (PMID 38861234, 2025). "In univariate analysis, increased levels of CXCL8, CXCL9, and CXCL10 showed an association with delirium, although this link was not evident in the multivariate analysis." (PMID 38861234, 2025).
diabetic kidney disease (1 paper, 2023). Progressive kidney disorder caused by vascular damage to the glomerular capillaries, in patients with diabetes mellitus. "We noted higher tissue mRNA expression of CXCL9 in biopsies from patients with AIN than in biopsies from patients with diabetic kidney disease, ATI, and individuals in the control group." (PMID 37395276, 2023).
diabetic neuropathy (1 paper, 2015). A chronic, pathological complication associated with diabetes mellitus, where nerve damages are incurred due to diabetic microvascular injury involving small blood vessels that supply these nerves, resulting in peripheral and/or autonomic nerve dysfunction. "The results of our studies suggest an important role for CXCL1, CXCL5, CXCL9, and CXCL12 in STZ-induced diabetic neuropathy." (PMID 25789329, 2015). "This study verifies that, in streptozotocin-induced diabetic neuropathy, the spinal protein levels of CXCL1, CXCL5, CXCL9, and CXCL12, but not CXCL11 and CXCL13, are upregulated." (PMID 25789329, 2015).
diffuse cutaneous Leishmaniasis (1 paper, 2012). A form of LEISHMANIASIS, CUTANEOUS caused by Leishmania aethiopica in Ethiopia and Kenya, L. pifanoi in Venezuela, L. braziliensis in South America, and L. mexicana in Central America. "The expression of CCL2 and CXCL9 was higher in CL tissue cells than in diffuse cutaneous leishmaniasis tissue." (PMID 22458474, 2012).
ductal adenocarcinoma (1 paper, 2024). "Indeed, plasma levels of IFN-ɣ-inducible chemokines CXCL9 and CXCL10 have been correlated with survival and chemotherapeutic efficacy in advanced ductal adenocarcinoma." (PMID 38167224, 2024).